PVT1 (Pvt1 oncogene)
Diseases named in the same sentence as PVT1 in open-access papers (continued):
Sharing a sentence is not in itself a finding about the gene and the disease.
tumor (continued). "A growing body of research has shown that lncRNA PVT1 has different degrees of abnormal expression in gynaecological malignancies and may affect a variety of tumour cell regulatory processes, which are closely related to the occurrence and progression of tumours." (PMID 38098223, 2024). "Subsequently, knockdown of the lncRNA PVT1 also led to suppressed induction of epithelial-mesenchymal transition (EMT), which is involved in tumor metastasis and invasion." (PMID 37371065, 2023). "A co‐expression analysis of tumor/adjacent tissue data from the CRC group revealed a correlation between the dysregulated miRNAs and CRC‐related genes (PVT1 and MYC) annotated in 8q24 region." (PMID 36366788, 2023). "There was a marked decrease in the level of PVT1 in the tumor tissues of LAMC, OV, ACC, THCA, and TGCT compared to the non-tumor tissues." (PMID 36624401, 2023). "For example, IL-6 or tumor-related factors can induce the overexpression of lnc C/EBPβ, LNC-CHOP, Olfr29-ps1, Pvt1 and RNCR3 in MDSCs, while chronic and low-dose stimulation of inflammation and tumor factors can also promote the down-regulation of lncRNAs." (PMID 36817434, 2023). "Previous findings revealed the competitive nature of enhancers in binding to PVT1 or c-MYC promoter, thus suggesting a tumor suppressor role for lncPVT1promoter." (PMID 37573419, 2023). "The results show that lncRNA Pvt1 downregulation considerably blocked the immunosuppressive function of G-MDSC in vitro, reducing tumour development and suppressing anti-tumour immune responses." (PMID 36817434, 2023). "Intriguingly, we found congruent significant high expression patterns of PVT1 and DUSP13 in tumor tissue compared with the normal counterpart." (PMID 36524545, 2023). "PVT1 knockdown inhibited DU145 cell migration and invasion, reduced tumor progression and metastasis, and increased survival time in vivo." (PMID 36831169, 2023). "Through subsequent screening of PVT1::MYC with FusionInspector, we identify a total of 32 samples (+9 TCGA tumor, +1 TCGA normal, and +3, −1 GTEx)." (PMID 37323575, 2023). "The gene pathway association between these overexpressed hypoxia genes would be via the PVT1/PRC2/STAT3 pathway and the ERK/HIF-1α/p70S6K cascade, which signals tumour-induced angiogenesis." (PMID 37048688, 2023). "Among them, six lncRNAs (LASTR, lnc-LAMC2, lnc-ZNF33B, PVT1, MIR205HG, and ENTPD1-AS1) were previously reported to play critical roles in the tumor recurrence and metastasis." (PMID 36894542, 2023). "Moreover, the functional diversity of PVT1 in tumors has been gradually proved, which not only directly regulates the malignant biological behaviors such as proliferation, invasion and migration, but also plays an indirect role in tumor microenvironment, metabolism and other aspects." (PMID 36941464, 2023). "They showed that lncRNA PVT1 expression was increased, whereas the lncRNA ZFAS1 expression was decreased compared with non-tumor parts." (PMID 36817434, 2023). "PVT1 upregulation stabilizes MYC expression, promotes tumor occurrence, and predicts a poor prognosis." (PMID 36195846, 2022). "Put together, LIMK2 is a novel prognostic biomarker and correlates with tumor immune cell infiltration in LUSC, and the expression of LIMK2 is regulated by the PVT1 and DHRS4-AS1/miR-423-5p axes." (PMID 35273591, 2022). "Our data demonstrated that PVT1 circular RNA (CircPVT1), MYC, and CASC11 are significantly (p < 0.05) overexpressed in CRC tumor samples compared to normal margin tissues." (PMID 36052265, 2022). "In conclusion, these results suggest that PVT1 plays a significant role in promoting TC, which is related to TNM and LNM stages, and TC tumor invasion, and can be used in the diagnosis of thyroid nodules." (PMID 36195846, 2022). "Overexpression of lncRNA PVT1 activates the STAT3/VEGFA pathway, sparks the angiogenesis in tumor cells, and vigorously boosts GC progression in vitro and in vivo." (PMID 35012438, 2022).
tumor (continued). "Circ PVT1 mediates CDDP and MTA resistance via the miR-145-5p/ABCC1 axis, and Circ PVT1 knockout sensitizes tumor cells to CDDP and MTA." (PMID 36338714, 2022). "As expected, many common tumor‐related lncRNAs, such as MALAT1, NEAT1, HULC, and PVT1, were identified in the H3K27ac chromatin immunoprecipitation sequencing (ChIP‐seq) data." (PMID 36307901, 2022). "Important promoters of tumour angiogenesis can serve as therapeutic targets, including MALAT1, TUG1, LNC00323-003, PVT1, and MIR503HG." (PMID 35052495, 2022). "We found that lowering PVT1 resulted in reduced proliferation (MTT assay - P < 0.0001), migration potential of the tumor cells (transwell migration assay–P = 0.003) and clonogenic survival (P = 0.0088) in SK-OV3." (PMID 35820706, 2022). "Overexpression of PVT1 greatly promoted the GC cell epithelial-to-mesenchymal transition (EMT) process and tumor metastasis in vitro and in vivo." (PMID 34179148, 2021). "Cell lines and xenograft tumours with PVT1 or AGO1 knockdown were used to investigate the effects on cell death and tumour growth." (PMID 34288373, 2021). "Differently from lncRNA DLEU1 and lncRNA PVT1, the expression of ncRNA LOC646588 was downregulated in tumor tissues versus normal tissues, but the hazard ratio of ncRNA LOC646588 was greater than 1, and the P-value was less than 0.01." (PMID 34790582, 2021). "PVT1 silencing also modulated the miR-128-3p/Gremlin 1 (GREM1) axis resulting in inhibition of the bone morphogenetic protein (BMP) signaling pathway and tumor growth." (PMID 34322395, 2021). "In our study, we discovered the regulatory role of miR-152-3p in the lncRNA PVT1/VEGFA axis, especially exosomes, which are closer to the exploration and application of tumor microenvironment." (PMID 34336125, 2021). "The present study also suggested that the expression of PVT1 and DLEU1 in tumor tissues was notably higher than that in normal tissues." (PMID 34790582, 2021). "PVT1, MALAT1, miRNA-186 and miRNA-101 levels were correlated with E-cadherin, tumor stage, lymph node and distant metastasis." (PMID 34200314, 2021). "LINC00900, MIR210HG, MIR22HG, PVT1, and SNHG18 expression increased, whereas HAR1A, LINC00641, SLC25A21-AS1, and SNAI3-AS1 expression decreased with tumor grade." (PMID 34288803, 2021). "PVT1, TRPM2‐AS, and TCONS_00012883 were most significantly higher in 24 pairs of tumor tissues than normal tissues." (PMID 33135346, 2020). "However, under the PVT1 promoter mutational rearrangements found in tumor cells, and even epigenetic inactivation, PVT1 intragenic enhancer elements interact preferentially with MYC promoter, thus boosting the transcription of MYC oncogene and its oncogenic activity of tumor cells." (PMID 32083000, 2020). "Most importantly, PVT1 ASOs efficiently inhibited the PVT1 level and suppressed GAC cell colony formation and invasion in vitro and delayed tumor growth in a PDX model in vivo." (PMID 33076512, 2020). "We next examined PVT1 expression in ten freshly frozen normal nasopharyngeal specimens and in ten clinical NPC tumor samples." (PMID 31320749, 2020). "Finally, the expression of miRNA-18a/HIF1A/PVT1 was validated in both cell lines and clinical tumor samples by utilizing quantitative polymerase chain reaction (qPCR) analysis, which could be used as potential biomarkers for early diagnosis and target for treatment." (PMID 32226492, 2020). "PVT1 ASOs effectively suppressed PVT1 levels in patient-derived cells and GAC cell lines, inhibited tumor cell colony formation and invasion in vitro, and suppressed tumor growth in vivo." (PMID 33076512, 2020).
tumor (continued). "In addition, PVT1 and circPVT1 regulate immune responses: the overexpression of the linear form in myeloid derived suppressor cells induced immune tolerance in preclinical tumor models and circPVT1 showed immunosuppressive properties in myeloid and lymphoid cell subsets." (PMID 32228602, 2020). "We next evaluated PVT1 expression in normal tissue, primary GAC tissue, and PC tumor cells using qPCR and found that it was significantly upregulated in primary GAC tissue and PC cells compared to in normal tissue." (PMID 33076512, 2020). "For instance, PVT1, CCAT1, CCAT2, PCAT1, and MINCR lncRNAs have been identified among the most promising lncRNAs regulating Myc activity in tumor cells." (PMID 33142861, 2020). "lncRNAs such as PVT1 and UCA1 can be packaged into exosomes to link the crosstalk between stromal cells and tumor cells partly through autophagy regulation, thereby contributing to pre-metastasis niche formation." (PMID 33050642, 2020). "The expression of PVT1 and ERG in tumor tissues was enhanced by BMSC-EXO injection, while it was reduced by BMSC-EXOsi-PVT1 injection." (PMID 31699956, 2019). "Other examples of lncRNAs that are secreted from tumor exosomes include LUCAT1 and PVT1 in exosomes of liver cancer." (PMID 31658672, 2019). "LncRNA Pvt1 knockdown suppresses G-MDSC-mediated immunosuppression in vitro by decreasing the level of ROS and ARG1, and delays tumor progression in tumor-bearing mice." (PMID 31448238, 2019). "This study presented a positive correlation of PVT1 and RUX2 in CRC tumor tissues in that PVT1 increased RUX2 expression." (PMID 31744051, 2019). "Mechanistically, PVT1 lncRNA knockdown increased phosphorylated LATS1 and phosphorylation of YAP1 which led to inactivated YAP1 leading to tumor growth inhibition." (PMID 31601234, 2019). "Tumor-infiltrating PMN-MDSCs and M-MDSCs show increased expression of Pvt1 in tumor mouse models, and overexpression in the splenic MDSCs of those mice." (PMID 31404149, 2019). "High expression levels of lncRNA HEGBC, PAGBC, PVT1 and UCA1 predicted high tumor node metastasis (TNM) stages, while lncRNA LET, GCASPC and MEG3 indicated low TNM stages." (PMID 31297033, 2019). "As a sponge of miR-20a-5p, PVT1 can increase the expression of unc-51-like kinase 1 (ULK1), which promotes autophagy in tumor cells, thereby providing sufficient energy for tumor growth." (PMID 31380270, 2019). "Compared with the control group, the BMSC-EXO injection markedly increased tumor growth, while the injection of BMSC-EXOsi-PVT1 negated such response." (PMID 31699956, 2019). "LncRNAs known to be a regulatory factor of tumor stem cells included GAS5, NEAT1, SOX2OT, Malat-1, HOTAIR, PVT1, BCAR4 and RBM5-AS1." (PMID 31143372, 2019). "Taken together, these results suggested that the mutual regulation of PVT1 and YAP1 exists in EAC cells and simultaneous inhibition of PVT1 and YAP1 lead to more effective suppression of EAC tumor growth than that of either gene alone." (PMID 31601234, 2019). "A characteristic example is the role of the PVT1 lncRNA promoter that limits MYC expression in breast cancer, essentially acting as a tumor-suppressor element." (PMID 31658672, 2019). "Thus, the mechanism of coamplification of PVT1 and MYC in tumor cells may involve a positive feedback pathway in which c-Myc increases the transcription of PVT1 by binding to E-boxes located in the PVT1 promoter region, which results in the increased expression of PVT1." (PMID 31309249, 2019). "A similar phenomenon was previously shown for PVT1 (a gene in the vicinity of the MYC locus), since MYC/PVT1 co-amplification is required for efficient tumour formation in MMTV-Neu-driven tumours." (PMID 30082728, 2018).
tumor (continued). "Therefore, serum levels of PVT1 may also be different in patients with different sizes of tumor." (PMID 29760583, 2018). "Our results showed that the relative expression levels of CYTOR and PVT1 were up-regulated, while HAR1A and MIAT were significantly down-regulated in diffuse glioma specimens compared to non-tumor tissues (all P <0.001)." (PMID 29108264, 2017). "As epithelial-mesenchymal transition (EMT) is an important enabling property of tumor metastasis, we performed wound healing assay and Transwell assay in 786-O and ACHN cell lines to explore the effect of PVT1 on cell migration and invasion." (PMID 29156724, 2017). "Univariate Cox regression analysis indicated that neoplasm histologic grade, TNM stage, distant metastasis, and PVT1 expression were potential predictors for OS and DFS." (PMID 29156724, 2017). "We previously showed that lncRNA PVT1 is significantly upregulated in LAD tissues and cells, and that it promotes cell proliferation through epigenetically repressing tumor suppressor LATS2 expression by interacting with EZH2." (PMID 28109288, 2017). "Subsequent analyses demonstrated that the expressions of PVT1 and CYTOR were up-regulated, while HAR1A and MIAT were down-regulated in diffuse glioma samples compared to non-tumor tissues." (PMID 29108264, 2017). "Knockdown of PVT1 inhibited proliferation and migration of ESCC in vitro and suppressed tumor growth in vivo." (PMID 28404954, 2017). "To explore the relationship between PVT1 and 8q24 in GC, we checked the genomic amplification of PVT1-MYC region in 30 pairs GC tumor samples by qPCR." (PMID 25890171, 2015). "Compared with the corresponding non-tumor liver tissues of the HCC cohorts, PVT1 expression was significantly increased in the cancerous tissues of the patients in cohort one (P=0.0016) and cohort two (P=0.0274)." (PMID 25624916, 2015). "Univariate analysis demonstrated that the significant prognostic factors for HCC recurrence were tumor size, tumor number, histopathological grade, PVTT, preoperative AFP level, TNM stage and PVT1 expression (all P<0.05)." (PMID 25624916, 2015). "Among them, HOTAIR, PVT1, H19, MALAT1, GHET1 and HULC were significantly higher in tumor tissues compared with control tissues." (PMID 26096073, 2015). "The highly expressed ALKBH5 reduces the m6A modification of PVT1 to suppress the YTHDF2-mediated m6A-dependent degradation, leading to PVT1 overexpression, which results in the promotion of OS cell proliferation and tumor growth." (PMID 40958857, 2025). "Importantly, MYC is critically dependent on PVT1 levels: inhibition of PVT1 results in reduced MYC protein levels and impaired tumor growth, indicating that PVT1 plays a critical role in MYC-driven tumorigenesis." (PMID 40027648, 2025). "Although it is still unidentified whether PVT1 is critical in tumour growth, our results demonstrated that ALKBH5 might regulates tumour progression via PVT1 RNA." (PMID 38098223, 2024). "Xenograft tumor experiments of nude mice in vivo, and colony formation, CCK-8, and EdU assays in vitro demonstrated that knockdown of PVT1 could widely suppress cell proliferation in vivo and in vitro." (PMID 36944636, 2023). "After that, we investigated whether the lncRNAs PVT1 and CCAT1 were expressed differently in tumor tissues taken from ESCC patients to see if there was a link between the two." (PMID 36624401, 2023). "Following that, we investigated whether the lncRNAs PVT1 and CCAT1 are similarly overexpressed in other tumor types." (PMID 36624401, 2023). "Many studies have found that lncRNAs, including PVT1, are differentially expressed in tumor tissues compared with non-tumor tissues." (PMID 36195846, 2022).
tumor (continued). "MYC (but also PVT1 at a lower level) is overexpressed in the two patients with HPV integration in the MYC/PVT1 region, as compared to the expression in the 42 other HNSCC tumours." (PMID 35398964, 2022). "Meanwhile, the overexpressed lncRNA PVT1 can elevate epithelial mesenchymal transition (EMT) marker levels, and promote EMT processes and tumor metastasis of GC in vitro and in vivo, by binding to miR-30a and increasing its target gene Snail expression by acting as a competing endogenous RNA." (PMID 35183057, 2022). "In addition, lincRNA-p21 has been described as a tumor suppressor, while HOTAIR, MALAT-1, H19, PVT1, ANRIL, and GIHCG, have been characterized as oncogenic lncRNAs." (PMID 36360316, 2022). "Besides, PVT1 shRNA also decreased tumor cell invasion and metastasis in HCT116 cells and SW620 cells, while PVT1 upregulation increased these phenotypes in Caco-2 and SW480 cells." (PMID 36266267, 2022). "PVT1 also promotes the proliferation, invasion, and EMT of various tumor cells." (PMID 36195846, 2022). "A positive correlation between PVT1 with the tumor stage (r = 0.4412, p = 0.0021), the lymph node status (r = 0.3181, p = 0.0312) and the distant metastasis (r = 0.3018, p = 0.0415) of the CRC patients, respectively." (PMID 34200314, 2021). "LncRNA PVT1 was found to be upregulated in PTC—combined with IGF1R overexpression and miR-30a downregulation—and is related to TNM stage, lymph node metastasis, and tumor infiltration." (PMID 35186709, 2021). "Moreover, the upregulated expression of several lncRNAs, such as LINC00152, MALAT1, PVT1, UCA1, etc are also correlated with poor prognosis, tumor progression, lymph node invasion, and TNM stage advancement." (PMID 34944491, 2021). "For instance, HCG18, PVT1, and LINC02381 are highly expressed in BC and expedite tumor progression." (PMID 37304675, 2021). "Studies have identified complementary base pair regions between the majority of the lincRNAs located in 8q24.21 (PVT1, CCAT1, PCAT1, CCAT2, CASC11, PRNCR1, CASC19, CCDC26) and miRNAs which have been previously identified as tumour suppressors." (PMID 33499210, 2021). "Then the expression of PVT1, miR-503, and ARL2 was examined in the resected tumor tissues." (PMID 33817293, 2021). "Here, we summarize ncRNAs with tumor-promoting functions: HOTAIR, HOTTIP, MALAT1, lncRNA H19, lncRNA PVT1, circ-RNA ciRS-7, circ-0030235, circ-RNA_100782, circ-LDLRAD3, circ-0007534, circRHOT1, circZMYM2, circ-IARS, circ-RNA PDE8A, miR-21, miR-155, miR-221/222, miR-196b, miR-10a." (PMID 32257946, 2020). "They demonstrated that MSC-AS1, POLR2J4, EIF3J-AS1, SERHL, RMST, and PVT1 were significantly upregulated in tumor samples compared to nontumor samples and were significantly associated with RFS." (PMID 33520012, 2020). "In granulocytic myeloid-derived suppressor cells (G-MDSCs), PVT1 was up-regulated by HIF-1α under hypoxia and contributed to immunosuppression, given its depletion reduced the suppression of these cells on T-cells and delayed tumor progression." (PMID 32370770, 2020). "A previous study showed that PVT1 can increase the expression of miR-214 by enhancing the binding of enhancer of zeste homolog 2 (EZH2) to the miR-214 promoter, which ultimately promotes tumor cell proliferation and invasion." (PMID 31380270, 2019). "Although both PVT1 and MYC coexist in 8q24, are amplified in many tumor types and are both highly upregulated in our EAC patient-cohort, we found that upregulation of PVT1 is highly associated with advanced stage and poor prognosis, while MYC expression was less relevant to poor survival." (PMID 31601234, 2019). "PVT1 can counteract the inhibitive expression of gremlin 1 (GREM1) through sponging miR-128, thereby affecting the downstream proteins BMP2 and BMP4-mediated signaling pathway, thus maintaining the proliferative activity of tumor cells." (PMID 31380270, 2019).